TNF (tumor necrosis factor)
Diseases named in the same sentence as TNF in open-access papers (continued):
Sharing a sentence is not in itself a finding about the gene and the disease.
rheumatoid arthritis (continued). "For example, anti-human TNF monoclonal antibodies (infliximab and adalimumab) and soluble human TNFRII (etanercept) are highly efficacious in neutralising sTNF to treat rheumatoid arthritis." (PMID 28197335, 2017). "Golimumab is a human IgG1 TNF-α antagonist monoclonal antibody and is approved by the FDA for once-monthly subcutaneous administration as a treatment for rheumatoid arthritis, psoriatic arthritis, ankylosing spondylitis, and ulcerative colitis." (PMID 28357059, 2017). "Strikingly, ARNTL2 and NPAS2 were the core clock genes that were found to be disturbed in rheumatoid arthritis and they accompanied DEC2 by also reacting to TNF with increased expression." (PMID 30210560, 2017). "Furthermore, the efficacy of this approach is not altered by the association with two standard treatments of rheumatoid arthritis (RA), methotrexate and tumor necrosis factor (TNF) inhibition." (PMID 29062314, 2017). "Interestingly, in patients with rheumatoid arthritis and CKD the use of anti-TNF therapies was associated with slower loss of GFR, although it is unclear whether this is the result of interfering with rheumatoid arthritis disease activity or with CKD-associated progression of kidney injury." (PMID 28333114, 2017). "Tumour necrosis factor inhibitors (anti-TNF), including infliximab, etanercept, adalimumab, and golimumab, are widely used to treat immune-mediated diseases, including rheumatoid arthritis (RA), ankylosing spondylitis (AS), psoriasis (PsO), and psoriatic arthritis (PsA)." (PMID 29089055, 2017). "However, some patients with rheumatoid arthritis (RA) fail to response anti-TNF drugs due to the compensation of other inflammatory signals." (PMID 29137228, 2017). "Tumor necrosis factor alpha (TNF-α) inhibitors (TNFi) are an important agent for a number of inflammatory conditions, including rheumatoid arthritis (RA), ankylosing spondylitis, and inflammatory bowel disease." (PMID 28158970, 2017). "Tumor necrosis factor α (TNF-α) induces the expression and secretion of interleukin 8 (IL-8), which contributes to synovitis in rheumatoid arthritis (RA)." (PMID 28806729, 2017). "Moreover, instead of their ability to improve pain and tenderness, NSAIDs did not prevent disease progression in rheumatoid arthritis, a disease whose pathogenesis has been linked to the presence of pro-inflammatory cytokines, such as interleukin-1 (IL-1β) or tumor necrosis factor (TNF-α)." (PMID 28304349, 2017). "Current treatments for rheumatoid arthritis such as EMBREL and HUMIRA are quite specific, as they only target TNFα." (PMID 29230082, 2017). "Since TNF induces the expression of ARNTL2 and NPAS2, and they are the most disturbed genes in rheumatoid arthritis patients, we investigated how they regulate canonical E-box element compared to more studied ARNTL/NPAS2 complex." (PMID 30210560, 2017). "Blockade of granulocyte macrophage colony-stimulating factor (GM-CSF) and its receptor (GM-CSFRα) is being successfully tested in trials in rheumatoid arthritis (RA) with clinical results equivalent to those found with neutralization of the current therapeutic targets, TNF and IL-6." (PMID 27908288, 2016). "Levels of serum IL-8 have been shown to be significantly decreased in rheumatoid arthritis (RA) patients on anti-TNF-a therapy and reduced IL-8 production may reflect a significant amelioration in the inflammatory state of RA patients." (PMID 28005985, 2016). "Rheumatoid arthritis (RA) patients failing disease modifying antirheumatic drugs (DMARDs) may undergo anti-Tumor Necrosis Factor (anti-TNF) therapy." (PMID 27431503, 2016). "However, in autoimmune diseases, such as rheumatoid arthritis, TLOs have been shown to support local autoantibody responses (e.g., rheumatoid factor, ACPA/anti-CCP) linked with disease exacerbation and also influence the clinical response to mainstream biologics (e.g., anti-TNF)." (PMID 27752256, 2016).
rheumatoid arthritis (continued). "In the first year of follow-up, 63.5% of the patients persisted in their therapies with anti-TNF drugs (+/-DMARD) and 54.1% remained using DMARD in the group with rheumatoid arthritis." (PMID 27556964, 2016). "Studies of Caucasian patients with rheumatoid arthritis (RA) to identify genetic biomarkers of anti-tumor necrosis factor (TNF) response have used response at a single time point as the phenotype with which single nucleotide polymorphism (SNP) associations have been tested." (PMID 26776603, 2016). "Rheumatoid arthritis (RA) is a chronic inflammatory disease characterized by the destruction of articular cartilage and bone with elevated levels of proinflammatory cytokines, such as TNFα and IL-6, produced from the synovial tissue." (PMID 27123445, 2016). "DFO treatment on LPS-stimulated microglia prevented the increase of TNF-α, IL-1β, and IL6, and these cytokines have been shown to increase iron uptake in human monocytes from patients with rheumatoid arthritis." (PMID 27733186, 2016). "Two other early studies using animal models for rheumatoid arthritis have demonstrated that treatment with TSA, phenylbutyrate, or FK228 resulted in a decrease in the proinflammatory cytokine TNF-α." (PMID 27556043, 2016). "TNFα treatments can lead to peripheral neuropathy in cancer patients, and direct injection of TNFα in normal naïve animals results in pain-like behaviors similar to those described in human patients with rheumatoid arthritis (RA) and other inflammatory diseases." (PMID 25962909, 2015). "Tumor necrosis factor-alpha (TNFα) is a driving inflammatory mediator in rheumatoid arthritis (RA)." (PMID 26270649, 2015). "IL-7 enhances inflammation in various autoimmune disorders, including rheumatoid arthritis (RA) where it is increased in the synovial fluid (SF) and stimulates T-cells to produce various cytokines including tumor necrosis factor (TNF)-α, interferon (IFN)-γ, and IL-17." (PMID 26110994, 2015). "The introduction of biological agents such as anti-tumor necrosis factor (TNF)-α, has had a profound effect on the management of rheumatic arthritis, including both rheumatoid arthritis (RA) and ankylosing spondylitis (AS)." (PMID 25746854, 2015). "TNF-α and IL-17A act on fibroblast-like synoviocytes (FLS) and contribute to cytokine production, inflammation, and tissue destruction in rheumatoid arthritis (RA)." (PMID 25904914, 2015). "In rheumatoid arthritis, for example, TGF-β1 can suppress pro-inflammatory cytokines secretion, such as INF-γ and TNF-α, due to Treg cells induction in the periphery." (PMID 26312490, 2015). "This 28-week, phase IIIb study assessed safety and maintenance of response to certolizumab pegol (CZP) in a diverse population of rheumatoid arthritis (RA) patients, stratified by prior anti-TNF exposure, concomitant methotrexate (MTX) use and disease duration." (PMID 26568428, 2015). "Our results are in accordance with data from the Spanish registry BIOBADASER and the Italian MonitorNet database, which, along with two other studies, show a better anti-TNF-α retention rate in SpA as compared to rheumatoid arthritis (RA) in a larger number of patients." (PMID 25110401, 2014). "In the setting of rheumatoid arthritis, pro-inflammatory cytokine levels are elevated, which includes IFN-γ, TNF-α, IL-6, IL-1, GM-CSF and chemokines such as chemokine C-C motif ligand 2 (CCL2) and CCL13." (PMID 25501574, 2014). "In addition, TNF-α is a central cytokine that triggers inflammation in rheumatoid arthritis (RA), indicating that the inhibition of TNF-α is an effective treatment strategy for RA." (PMID 24692853, 2014). "Our results reveal a novel mechanism in TNF-α-induced inflammation and suggest new therapeutic strategies targeting 5-LOX for the treatment of rheumatoid arthritis." (PMID 25229347, 2014).
rheumatoid arthritis (continued). "In this study, our aim was to elucidate the role of four polymorphisms identified in a prior large genome-wide association study (GWAS) in which the investigators analyzed the responses of patients with rheumatoid arthritis (RA) to treatment with tumor necrosis factor inhibitors (TNFi)." (PMID 24612463, 2014). "We hypothesized that blocking these TNFα signals regulates the altered TNFα production in rheumatoid arthritis (RA) patients." (PMID 25037855, 2014). "The efficacy of anti-TNF plus methotrexate (MTX) treatment versus MTX monotherapy on clinical and radiological outcomes were compared in early rheumatoid arthritis (RA) patients in clinical practice by retrospective analysis of an observational cohort." (PMID 25059769, 2014). "While TNF blockade has proven to be a highly effective treatment for rheumatoid arthritis (RA), psoriatic arthritis (PsA) and psoriasis (Ps), three of the most prevalent immune mediated inflammatory disorders, recent evidence indicate that each disease arises by distinct pathophysiologic mechanisms." (PMID 25333715, 2014). "In rheumatoid arthritis, the inhibition of TNF-alpha-TNFR1 signaling by anti-TNF-alpha antibody or soluble TNF receptor has been established as an effective treatment for patients." (PMID 24685329, 2014). "Tumor necrosis factor inhibitor (TNFi) therapy is effective for rheumatoid arthritis (RA)." (PMID 24735586, 2014). "An example is Fc-fusion to the tumor necrosis factor (TNF) receptor (Etanercept, Enbrel®), which blocks binding of TNF-α to cellular TNF receptor and thus inhibits pro-inflammatory activity in rheumatoid arthritis patients." (PMID 25674083, 2014). "Nonbeneficial effects of anti-TNF immunotherapy in chronic inflammatory diseases (as rheumatoid arthritis and ankylosing spondylitis) associated with reactivation of Mycobacterium infection may be attributed to the depletion of the cytolytic CD8+perforin+/granulysin+ CTL population by Infliximab." (PMID 25140115, 2014). "IL32 levels showed positive correlations with tumor necrosis factor alpha, ESR, C-reactive protein, replication factor, and Disease Activity Score 28 genes in rheumatoid arthritis." (PMID 25100201, 2014). "Accelerations in active TB reactivations have also been described after the administration of tumor necrosis factor (TNF)α/IL-12/IL-23 blockers, which are used to treat inflammatory diseases, such as rheumatoid arthritis and Crohn's disease." (PMID 24991816, 2014). "In case of rheumatoid arthritis both, membrane and soluble IL7R, are induced by pro-inflammatory cytokine, especially TNFα." (PMID 25302706, 2014). "Tumor necrosis factor (TNF)-α is one of such key molecules, and anti-TNF-α therapies are used widely to treat human inflammatory disorders, such as rheumatoid arthritis and inflammatory bowel diseases." (PMID 24849253, 2014). "Moreover, a specific TNFα inhibitor, namely Etanercept (trade name Enbrel®), has been suggested to be efficacious against autoimmune diseases such as Crohn’s disease and is in clinical practice for the treatment of several peripheral inflammatory diseases such as rheumatoid arthritis." (PMID 24067145, 2013). "Several studies have demonstrated that ICAM-1 is upregulated during inflammation, asthma, rheumatoid arthritis and lung injury, and the expression of ICAM-1 is mediated by various inflammatory cytokines, particularly TNF-α." (PMID 24137303, 2013). "Treg modulation has been hypothesized as one of the mechanisms by which antitumor necrosis factor α (TNFα) agents exert their action in rheumatoid arthritis (RA) andinflammatory bowel disease (IBD)." (PMID 24063002, 2013). "In rheumatoid arthritis, the presence of anti-drug antibodies (ADA) against the first TNF inhibitor influences the outcome after switching." (PMID 23890223, 2013).
rheumatoid arthritis (continued). "We also performed an analysis of gene expression of the cytokines IL-1β and IL-6 and TNFα protein expression, since several studies have shown that inhibition of these cytokines may interfere with the degeneration of articular cartilage and subchondral bone in OA and rheumatoid arthritis." (PMID 24028507, 2013). "In rheumatoid arthritis synovial tissue, macrophages release VEGF through TNF-α, TGF-α, and IL-1 stimulation." (PMID 23725043, 2013). "Fisetin is known to suppress the production of tumor necrosis factor-α (TNF-α), IL-6, IL-8, and monocyte chemotactic protein-1 (MCP-1) in a rheumatoid arthritis model." (PMID 23710240, 2013). "Chitosan-siRNA particles targeting tumor necrosis factor-α (TNF-α), a factor secreted by peritoneal macrophages involved in inflammation in rheumatoid arthritis, were use in vivo in a murine arthritis model." (PMID 23676471, 2013). "In rheumatoid arthritis, TSP-2 suppressed the production of interferon-gamma and tumor necrosis factor-alpha, and induced the depletion of tissue-residing T-cells." (PMID 24376766, 2013). "The role of tumor necrosis factor (TNF) in inflammatory diseases such as rheumatoid arthritis (RA), juvenile idiopathic arthritis (JIA), and psoriasis is well established, as is the benefit of TNF inhibition in the treatment of these disorders." (PMID 24225257, 2013). "However, the persistent presence of TNF-α can contribute to chronic inflammatory conditions as seen in rheumatoid arthritis (RA)." (PMID 24025197, 2013). "In studies conducted in patients with active rheumatoid arthritis, peripheral blood CD4+CD25+ Tregs have shown reduced FOXP3 expression and suppressive function which can be reversed by treatment with an anti-TNFα monoclonal antibody (infliximab)." (PMID 24063002, 2013). "This proteinase has been suggested to be induced in response to proinflammatory cytokines such as tumor necrosis factor α (TNFα), interleukin-1 (IL-1), and IL-6 in articular cartilage under pathologic conditions, such as found in OA and rheumatoid arthritis (RA)." (PMID 23951098, 2013). "Recent studies have also shown that IL-27 is involved in anti-inflammatory functions, especially interfering with TNF-α or TH17 cells (or both) in autoimmune diseases, including multiple sclerosis, rheumatoid arthritis, and systemic lupus erythematosus." (PMID 22827855, 2012). "Nevertheless, TNF-α blockers are often used to treat rheumatoid arthritis (RA) and it was recently reported that obese RA patients receiving TNF-α blockers displayed improved fasting glucose and increased circulating adiponectin levels, possibly warranting more studies in the field." (PMID 23087692, 2012). "A summary of the physiologic effect of the inhibition of TNF and IL1 by microencapsulated compounds is described in the experimental models of sepsis and rheumatoid arthritis." (PMID 22348221, 2012). "Periodic assessment of gene expression for diagnosis and monitoring in rheumatoid arthritis (RA) may provide a readily available and useful method to detect subclinical disease progression and follow responses to therapy with disease modifying anti-rheumatic agents (DMARDs) or anti-TNF-α therapy." (PMID 23264777, 2012). "Serum levels of proinflammatory cytokines including TNF-α, IFN-γ, and IL-1α are increased in patients with rheumatoid arthritis and other autoimmune inflammatory disorders." (PMID 23217187, 2012). "Feeding patients with rheumatoid arthritis or multiple sclerosis fish oils rich in ω-PUFA, from which RvD1 is derived, can reduce TNF-α and IL-6 levels." (PMID 23199346, 2012). "Inhibition of the action of the proinflammatory cytokines TNF-α (Tumor necrosis factor-α) has illustrated both in animal models and in the clinic to be efficacious in the control of autoimmune diseases such as rheumatoid arthritis (RA)." (PMID 22837679, 2012). "TNF inhibitors (TNFi) have revolutionised the treatment of rheumatoid arthritis (RA)." (PMID 22102879, 2011).
rheumatoid arthritis (continued). "In patients with rheumatoid arthritis (RA), another chronic inflammatory disease and an important differential diagnosis in PMR, administration of TNF-α inhibitors has been a therapeutic success." (PMID 20854662, 2010). "Agents that target tumor necrosis factor (TNF) are highly effective in treating patients with active rheumatic disorders, such as rheumatoid arthritis (RA), ankylosing spondylitis (AS), or psoriatic arthritis (PsA)." (PMID 20553600, 2010). "Etanercept is a fully human fusion protein that inhibits tumor necrosis factor (TNF) and the inflammatory cascade, shown to be safe and effective in the management of patients with rheumatoid arthritis." (PMID 21083879, 2010). "Therefore, we determined the effect of TNF blockade in rheumatoid arthritis (RA) on the type I IFN response gene activity in relation to clinical response." (PMID 20096109, 2010). "Activation of p38α leads to the up-regulation of both TNFα and IL-1β, resulting in many chronic inflammatory diseases, such as rheumatoid arthritis (RA), inflammatory bowel disease, Crohn’s disease, and chronic obstructive pulmonary disease (COPD), as well as the other inflammatory disorders." (PMID 20957100, 2010). "TNF was the first cytokine convincingly demonstrated to contribute to chronic inflammation in several autoimmune diseases, including rheumatoid arthritis (RA) and Crohn disease." (PMID 20096109, 2010). "In rheumatoid arthritis and IBD, in which TNF-α plays an integral role, fatigue is markedly improved by treatment with anti-TNF-α agents." (PMID 20939923, 2010). "In controlled clinical trials in patients with rheumatoid arthritis, Tenovil exhibited ACR20 values substantially higher than the ones in control groups and comparable with the ACR20 values reported for TNF blockers." (PMID 19781067, 2009). "High affinity antibodies that target TNF-α, preventing its binding to TNF-αR1 and R2 receptors are clinically available for treatment of rheumatoid arthritis and Crohn's disease." (PMID 19904265, 2009). "As an example, the development of systemic lupus erythematosus-like symptoms during anti TNFα therapy in Rheumatoid Arthritis patients is due to accumulation of another cytokine, IFN-α, a direct consequence of the TNFα blockade." (PMID 19785746, 2009). "It was, therefore, decided to investigate whether treatment based on TNF blockade in rheumatoid arthritis (RA) affects the expression of synovial HMGB1." (PMID 18346273, 2008). "Peripheral blood neutrophils were cocultured either with rheumatoid arthritis synovial fibroblasts (RASF) or with conditioned medium from RASF that had been pre-exposed to recombinant human IL-17, TNFα or a combination of the two cytokines." (PMID 18433499, 2008). "TNF-α concentrations are increased in several disease states such multiple sclerosis (MS), inflammatory bowel disease (IBD), rheumatoid arthritis (RA), heart disease, and osteoporosis; and are often correlated with clinical impairment." (PMID 18652680, 2008). "Rheumatoid arthritis (RA) is an autoimmune disease characterized by hyperplasia of the synovial lining, inflammation, high levels of circulating and local IL-1β and tumor necrosis factor (TNF)α, and destruction of cartilage and bone." (PMID 17509138, 2007). "However, results of the ATTRACT (Anti-TNF Trial in Rheumatoid Arthritis with Concomitant Therapy) trial suggested that a higher dosage (10 mg/kg every 8 weeks) or a shorter perfusion interval may add benefit, which is reflected by the use of dosage increases in some studies." (PMID 16978395, 2006). "Several studies have shown dramatic therapeutic effects of anti-TNF-α antibodies, both in experimental collagen-induced arthritis and in the treatment of inflammatory diseases such as rheumatoid arthritis (RA), psoriatic arthritis, juvenile rheumatoid arthritis and Crohn's disease." (PMID 15743471, 2005).